HIF1A (hypoxia inducible factor 1 subunit alpha)
Diseases named in the same sentence as HIF1A in open-access papers (continued):
Sharing a sentence is not in itself a finding about the gene and the disease.
tumor (continued). "To date, early inactivation of the VHL gene, encoding a ubiquitin ligase, which marks hypoxia-induced factor α (HIF-1α) for proteasomal degradation, thus responsible for cellular oxygen sensing, is pointed out as a key tumor suppressor gene impaired in ccRCC." (PMID 31921677, 2019). "Here, we have found that elevated CHCHD4 expression increases tumour cell growth rate and HIF-1α protein levels in normoxia and hypoxia." (PMID 30886710, 2019). "HIF-1α is the main factor that regulates cellular response to hypoxia, being involved in tumor cells adaptation to intratumoral hypoxia, as well as in acquisition of resistance to chemotherapeutic drugs such as sorafenib." (PMID 31835431, 2019). "Studies have shown that apigenin reduces nuclear c-Myc and intracellular HIF-1α protein level in a dose-dependent manner, which leads to significant tumor inhibition." (PMID 30967777, 2019). "Hypoxia leads to the stabilization of HIF-1α and is a major stimulus for tumor cells to increase the expression of VEGF." (PMID 31036754, 2019). "In recent years, it has been reported that HIF-1α plays a prominent role in immune cells and regulates immune responses in the tumor microenvironment." (PMID 30925926, 2019). "Our group has demonstrated that oxygen nanobubbles (ONBs) reverse hypoxia and suppress HIF-1α activity in tumor cells (ONBs)." (PMID 31569523, 2019). "Accordingly, immunohistochemical analysis of 179 tumor specimens has revealed that hypoxia-inducible factor 1α (HIF1A) is frequently overexpressed in different cancer types, including breast, lung, and colon cancer." (PMID 31159361, 2019). "Carboxyl-terminus of Hsp70-interacting protein (CHIP) promotes the ubiquitylation and subsequent degradation of many tumor-related proteins, including HIF-1α, PTEN, c-Myc, Smad3, and Src-3 through the proteasomal machinery." (PMID 30736384, 2019). "The tumor perfusion enhancement, HIF-1α and VEGF expression reduction, and mature morphology of vessels after O2-MBs treatment demonstrated the feasibility of VN induced by local oxygen release." (PMID 31695774, 2019). "HIF‐1α has been correlated with tumor grade, metastasis, and poor prognostic outcomes in various cancers." (PMID 30653763, 2019). "A common molecular feature shared by such neoplasms is the chronic stabilization of the Hypoxia-Inducible Factor 1α (HIF1α) even in normoxia (pseudohypoxia)." (PMID 30728892, 2019). "The association between BAP1 loss and HIF1a expression was corroborated in the TCGA data with multivariate regression including BAP1 and chromosome 3, LBD, or tumour prominence." (PMID 31323773, 2019). "In a xenograft model of liver cancer, CCL28 upregulation promoted tumour growth and Treg recruitment in vivo in a HIF-1α dependent manner." (PMID 31835751, 2019). "Hypoxia-inducible factor-1α (HIF-1α) plays a critical role in response to tumor hypoxia and mediates tumor resistance to chemotherapy and radiotherapy." (PMID 31430901, 2019). "First, we assessed the expressions of Slug and Ubc9 in xenograft tumor specimen; and also examined the expressions of transcription factor, hypoxia-inducible factor 1-alpha (HIF1α), to evaluate their hypoxic status." (PMID 30612578, 2019). "Normalization of the tumor vasculature can affect HIF1α/VEGFa feedback and reduce TC recruitment or vasculogenic mimicry (VM) formation, leading to better clinical responses in cancer patients." (PMID 31266540, 2019). "The ability of YY1 to regulate tumor cell lipid metabolism in a HIF-1α-independent manner also provides evidence of the importance of HIF-1α-independent pathways in tumorigenesis." (PMID 31695789, 2019). "Tumor cells, aPSC, and TAM express GPCR β-adrenergic receptors ADRBA1,-A2, -B1, -B21 that signal via the associated trimeric G-proteins, HIF-1α, and ERK/MAPK, which in concert promote tumor growth and metastasis." (PMID 31921628, 2019). "We next examined HIF-1α expression in the primary tumor tissues by IHC staining and western blotting." (PMID 31106156, 2019).
tumor (continued). "The relationship between increased levels of HIF-1α, transactivation and gene expression is poorly described in tumor cells exposed to OSA." (PMID 30669593, 2019). "Since Multimerin-2 was previously shown to affect HIF-1α expression we also assessed the hypoxic levels in this tumor." (PMID 31263680, 2019). "Several studies report that the hypoxic tumor microenvironment regulates different transcription factors mediated by HIF-1α." (PMID 31993365, 2019). "Tumor hypoxia can also be inferred from the expression of various endogenous proteins, such as HIF-1α, glucose transporters-1 or -3, vascular endothelial growth factor-A, and carbonic anhydrase-9." (PMID 30669417, 2019). "Regulation of the enzyme carbonic anhydrase IX as well as probably AQP1 by HIF-1α furthers tumor progression and poorer survival in several other solid tumors." (PMID 31600976, 2019). "For example, molecular targeting of C-X-C motif chemokine receptor 4 (CXCR4) on vascular endothelial cells induced tumor angiogenic inhibition triggered necrosis (TAITN) in oral cancer, although HIF-1α was induced in the hypoxic and the necrotic tumor tissue." (PMID 31533245, 2019). "This is likely because the tumor continues to release large amounts of HIF1α and VEGF and induces robust microangiogenesis." (PMID 31428651, 2019). "The expression status of SNHG12-miR-199a-5p-HIF1α axis was also analyzed in xenograft tumor tissue at mRNA and protein level, which was consistent with our previous results acquired from cell culture." (PMID 31114448, 2019). "Previous studies have reported that emetine suppresses the expression of HIF-1α, which plays a central role in tumor progression, invasion, and metastasis." (PMID 31775307, 2019). "Kim found ELH can attenuate HIF-1α accumulation by blocking phosphorylation of AKT/mTOR/p70S6K to inhibit tumor angiogenesis." (PMID 31022939, 2019). "HIF-1α is the master regulator of cellular response to hypoxia typical to a pro-proliferative and pro-migratory tumor microenvironment." (PMID 31695026, 2019). "Expression of HDACs class IIa was elevated in hypoxic tumor regions expressing high levels of HIF-1α." (PMID 30837601, 2019). "Vice versa, hypoxia rapidly fosters energy production in tumor cells via glycolysis through hypoxia-inducible factor 1-alpha (HIF-1α)-mediated transcriptional control." (PMID 31402913, 2019). "The CAIX protein (IHC) level of the tumor cells was correlated, as expected, with the HIF1α-protein (IHC) expression (p = 0.015) in the same tumor samples." (PMID 30654595, 2019). "The highly hypoxic tumor microenvironment promotes HIF1α expression in TILs, which further promotes glycolysis and decreased reliance on OXPHOS by the T cells." (PMID 31379821, 2019). "Under tumor conditions however, hypoxia and HIF-1α seem to drive the development and function of immunosuppressive myeloid cells like TAMs and MDSCs." (PMID 30804946, 2019). "Presumably, lowering the O2 concentration induces pro-angiogenic mechanisms, e.g. VEGF expression by the tumor cells via stabilization of hypoxia-induced factor (HIF1α), triggering endothelial cell proliferation and migration." (PMID 31666641, 2019). "Angiogenesis can be induced by hypoxia directly through HIF1α, but has also been described as a secondary process to tumor necrosis, induced by inflammatory cytokines from necrotic cells." (PMID 30640942, 2019). "In the xenograft tumor model in nude mice, melittin treatment significantly suppressed the tumor growth, VM formation, and HIF-1α expression in the tumor." (PMID 31057657, 2019). "Elevated HIF-1α expression was reported linking with tumor metastasis, resistance to therapy, and poor survival." (PMID 30038060, 2019). "HIF-1α initiates over-expression in tumor cells and raises the activity of a number of glycolytic protein isoforms which are different to those present in non-malignant cells." (PMID 30761299, 2019).
tumor (continued). "In vivo studies reveal that the administration of sanguinarine inhibits tumor growth and HIF-1α signaling, inhibits the expression changes of EMT markers as well as Smad and PI3K-AKT pathway proteins." (PMID 31819036, 2019). "HIF-1α is a protein ubiquitously expressed and notably produced by tumor cells in hypoxic condition." (PMID 31903166, 2019). "Overexpression of hypoxia-inducible factor-1 alpha (HIF-1α) in tumor sections validated hypoxic conditions in the tumor core." (PMID 31023373, 2019). "First, as a tumor grows, the tumor microenvironment becomes hypoxic allowing the stabilization of HIF-1α." (PMID 31354653, 2019). "Hypoxia-inducible factor 1α (HIF-1α) is connected with mechanisms of tumor invasion capacity, radiotherapy, and chemotherapy resistance." (PMID 30678221, 2019). "HIF1a is an important transcription factor that helps the tumor cells acquire aggressive and drug-resistant phenotypes, and it is identified as a down-stream molecule of the mTOR signal pathway." (PMID 29416762, 2018). "HIF-1α produced by tumor cells plays a vital role in an adaptive response to hypoxia by modulating various cellular functions like proliferation, apoptosis, angiogenesis, and anaerobic glycolysis." (PMID 29461122, 2018). "In order to adjust to the hypoxic microenvironment, the transcription factor HIF1α modulates hundreds of genes in tumor cells, allowing proliferation, cell survival, invasion, angiogenesis, and drug resistance, hallmarks of cancer." (PMID 29882856, 2018). "The Ha2bm promoter enabled the oncolytic Ad to actively replicate and disperse through the central and hypoxic tumor regions, expressing high levels of HIF-1α." (PMID 29396500, 2018). "HIF-1α is a subunit of the HIF transcription factor that regulates expression of several genes involved in tumor proliferation, metabolism, and adaptation to hypoxic stress." (PMID 29619216, 2018). "For instance, subcutaneous inoculation of HIF-1α-deficient and VEGF-deficient transformed astrocytes resulted in reduced vessel density and tumor growth." (PMID 30420794, 2018). "While HIF-1α deletion reduces tumour vascularisation and tumour growth, HIF2-α deletion, on the contrary, is able to augment angiogenesis with the formation of a more disorganised vascular system and more hypoxic tumours." (PMID 29362402, 2018). "Other Hif members also cooperate with HIF1a to play an important role in tumour progression, including tumour angiogenesis." (PMID 30060750, 2018). "It has been shown that HIF-1α is a leading regulator of tumor angiogenesis following hypoxia, because it regulates the expression of several pro-angiogenic factors, such as the VEGF31–33." (PMID 29449553, 2018). "This reflects the fact that tumor cells exhibit differing hypoxia-inducible factor 1α (HIF-1α) expression and regulation under mild 1% O2 and severe 0.1% O2 hypoxic conditions." (PMID 30216369, 2018). "In tumor tissue, the HIF-1α mRNA level correlated with the EGFR protein level (correlation coefficient: +0.36; p = 0.001), in addition, the EGFR mRNA correlated with EGFR protein level (correlation coefficient: +0.53; p < 0.001)." (PMID 30513863, 2018). "Monocytes from patients with OSA increased the tumor-induced microenvironment and exhibited an impaired cytotoxicity in a 3D tumor in vitro model as a result of the increased HIF1α secretion." (PMID 29997451, 2018). "One of the effects of increased amount of HIF-1α is the formation of new blood vessels, which results in tumor regrowth." (PMID 29743548, 2018). "However, those patients with recurrence after the primary tumor resection had a 3.1-fold (univariate Cox’s regression hazard analysis) increased risk of tumor-related death when the expression was less than 4.7 copies of HIF-1α mRNA per copy of HPRT mRNA in their primary tumors (p = 0.003)." (PMID 30513863, 2018).
tumor (continued). "Further insight on the ALDH1A1 mechanism as a driver of tumor progression was gained by examining two signalling pathways, i.e. retinoic acid and HIF-1α." (PMID 30541574, 2018). "HIF-1α within central vital tumor areas was undetectable in most tumors but ranged up to 20% in one tumor with a median of 0%." (PMID 30129426, 2018). "Tumor microarray analysis demonstrated that HIF1α and HIF2α are individually and jointly co-expressed in a majority of primary and metastatic ccRCC biopsies." (PMID 30380599, 2018). "Recently, the C-terminal truncation of the VDAC1 isoform, termed VDAC1-ΔC, has been observed in chemoresistant late-stage tumor cells grown under hypoxic conditions with activation of the hypoxia-response nuclear factor HIF-1α." (PMID 29596470, 2018). "The positivity rate of HIF-1α as well as ABCG1 around necrotic areas were significantly reduced in the ABCG1-depleted tumor compared with the control tumor." (PMID 30364132, 2018). "For example, daily intraperitoneal injections of vitamin C slowed tumor growth in the mice and downregulated HIF-1α and downstream gene products to a greater extent than injections every other day." (PMID 30190680, 2018). "In support of our findings that QM-PDAC tumours have a Warburg phenotype, we found elevated levels of HIF1A and concomitantly lower levels of its corepressor, SIRT6." (PMID 30018740, 2018). "HOXA9 acts as a tumor suppressor and inhibits glycolysis in cSCC in vitro and in vivo by negatively regulating HIF-1α and its downstream glycolytic regulators, HK2, GLUT1 and PDK1." (PMID 29662084, 2018). "Overexpression of HIF‐1α and HIF‐2α leads to the upregulation of genes involved in proliferation, angiogenesis, and glucose metabolism, and is associated with tumor progression in several cancers including RCC." (PMID 30107094, 2018). "HIF-1α plays an important role in hypoxic responses and induces the transcription of various genes responsible for tumor angiogenesis, invasion and metastasis." (PMID 30200948, 2018). "Specifically, UBE2CP3 promotes HCC cell secretion of VEGFA into the tumor microenvironment by activating the ERK/p70S6K/HIF-1α pathway; this VEGFA alters EC proliferation, migration and tube formation capacities." (PMID 29866133, 2018). "Several theories were suggested to explain normoxic HIF-1α up-regulation in PCA, including HIF-1α stabilization relying on tumor hypoxia, increased HIF-1α mRNA expression, gene amplification, and single-nucleotide polymorphisms (SNPs)." (PMID 30216369, 2018). "Hypoxia-inducible factor-1α (HIF-1α) plays an important role in tumor cell invasion, metastasis, immortalization, tumor angiogenesis, and cancer function." (PMID 29531823, 2018). "In our preclinical model, an immunohistochemical study confirmed the nuclear HIF-1α expression in tumor cells in the bone metastases of MDA-MB-231 cells in nude mice, which co-localized or surrounded the pimonidazole-positive cells." (PMID 30423905, 2018). "As HIF-1α plays a central role in the regulation of glycolytic phenotype of tumor cells, we performed Western blot analysis to test the effect of drugs on HIF-1α under hypoxic and normoxic conditions." (PMID 29958416, 2018). "In particular, CAIX is a HIF-1α-induced, cell-surface enzyme that regulates pHi and promotes tumor cell survival." (PMID 29517989, 2018). "A hypoxic tumor environment leads to necrosis of cells located far from vessels, but activation of HIF-1α in surviving tumor cells closer to the vessels." (PMID 30250643, 2018). "For histological characterization of our cohort, we evaluated the extent of necrosis, P-PRAS40, P-RPS6 and HIF-1α in perinecrotic as well as in vital tumor areas." (PMID 30129426, 2018).
tumor (continued). "MALAT1 induces autophagy in tumor cells under hypoxia and stabilizes HIF-1a in human liver L-02 cells." (PMID 29435112, 2018). "It was reported that activation of autophagy inhibits tumor metastasis through the induction of HIF-1α." (PMID 30134829, 2018). "Compared to the control group, the expression of HIF-1α in tumor tissue in the 3 treatment groups all decreased, and the differences were statistically significant (P=0.002, 0.011, 0.000<0.05)." (PMID 30087869, 2018). "In conclusion, these studies reveal that by regulating several pathways including metabolic reactions and miRNA expression, HIF-1α critically regulates the function and maintenance of MDSCs within the hypoxic tumor environment." (PMID 30425715, 2018). "T cell specific deletion of HIF-1α resulted in reduced tumor infiltration and killing, as well as an altered tumor vascularization." (PMID 29762526, 2018). "High amounts of lactate in the tumor microenvironment stimulate TAM polarization into the M2-like phenotype by stabilizing HIF-1α." (PMID 30076128, 2018). "Tumor aggressiveness stimulated by HIF-1α has been found to rely on collagen remodeling enzymes, including PLOD2, and the prolyl hydroxylases, but PLOD3 is poorly studied." (PMID 29644003, 2018). "As such, high levels of HIF-1α have been reported to negatively influence the response to cisplatin treatment in various tumor types, including lung cancer." (PMID 29690507, 2018). "HIF-1α is correlated with vascular density, tumor metastasis, angiogenesis, poor patient prognosis, as well as anticancer drug resistance." (PMID 29416751, 2018). "Metabolic adaptation upon oxygen deprivation is a common feature of tumor cells that rapidly foster energy production via glycolysis through HIF1α-mediated transcriptional control." (PMID 29649100, 2018). "Destruction of neoplastic blood vessels is associated with the appearance of inflammation, hypoxia and activation of HIF-1α protein in tumors, which in turn leads to formation of new blood vessels and tumor regrowth." (PMID 29743548, 2018). "In hypoxia-related tumor radioresistance, HIF-1α plays significant roles and is an important prognostic factor after radiation therapy." (PMID 30355300, 2018). "Pyruvate kinase M2 activates mTORC1 by phosphorylating AKT1S152 and PKM2 promotes tumor angiogenesis by regulating HIF-1α through NF-κB activation." (PMID 29449541, 2018). "Tumor cells derived lactic acid (the final product of glycolysis) mediated by HIF-1α can acts as an immunosuppressive metabolite and direct differential myeloid cell functions such as M2-like polarization." (PMID 30619850, 2018). "In order to verify, the involvement of HIF1α in the resistance of MOLP8/R cell line to NK cell lysis, we treated the tumor cells with HIF1α inhibitor cryptotanshinone at two different concentrations, 10 and 15 μM, for 48 h." (PMID 29882856, 2018). "Previous studies have indicated that HO-1 can trigger and regulate HIF-1α expression in hypoxic tumor cells." (PMID 29888265, 2018). "Experiments using the active form of HIF-1α in human skin fibroblast showed increased tumor growth when co-injected together with MDA-MB-231 cells, whereas HIF-2α did not have an effect." (PMID 29896451, 2018). "Depletion of HIF-1α or HIF-1α target genes such as LDH or carbonic anhydrase IX (CAIX) in 4 T1 cells inhibits primary tumor growth, therefore decreasing subsequent macrometastasis." (PMID 30005601, 2018). "Elaiophylin not only downregulated VEGFR2-mediated signal transduction in endothelial cells, but also expression of HIF-1α in tumor cells, leading to suppression of tumor angiogenesis." (PMID 29498688, 2018). "MDM2 as one of E3 Ub-protein ligases is able to bind to p73 at the N-terminal region and inhibits tumor angiogenesis by promoting HIF-1α degradation." (PMID 29362483, 2018).